MIR202HG (MIR202 host gene)
Gene: Long non-coding RNA gene on chromosome 10 (133,246,471 to 133,248,080, reverse strand). Ensembl gene ENSG00000166917.
Gene Ontology:
Cellular component: RISC complex
Diseases named in the same sentence as MIR202HG in open-access papers:
MIR202HG is named in the same sentence as 1 disease in open-access papers, as found by Europe PMC text mining. Sharing a sentence is not in itself a finding about the gene and the disease. The quoted sentences say what the papers report.
gastric cancer (1 paper, 2023). A primary or metastatic malignant neoplasm involving the stomach. "In this study, mGWAS-based studies localized four non-coding RNAs associated with gastric cancer prognosis, namely, MIR202HG (MIR202 host gene), MIR378D1, LINC02472, and LINC02310." (PMID 37894938, 2023).